IL6 (interleukin 6)
Diseases named in the same sentence as IL6 in open-access papers (continued):
Sharing a sentence is not in itself a finding about the gene and the disease.
diabetes (continued). "IPA also predicted activation of TNF-α, IL-6, and IL-1β cellular signaling pathways, where these key immunoregulators are known to be associated with diabetes-induced metabolic inflammation." (PMID 35304484, 2022). "Emerging evidence has showed that numerous cytokines, including TGFβ, IL-6, IL-1β, and IL-21, are associated with bone remodeling in diabetes." (PMID 35993048, 2022). "ROS produced by mitochondrion are implicated in chronic inflammation, cancer progression, diabetes mellitus, and atherosclerosis, and it also contributes to LPS-mediated production of pro-inflammatory cytokines IL-1β, IL-6, and TNF-α." (PMID 36012352, 2022). "Mortality was inversely associated with 25OHD levels controlling for age, gender, diabetes, IL-6, CRP, LDH, neutrophil cell, lymphocytes, and platelets levels." (PMID 34126960, 2021). "In diabetic patients and rat models, expression of miR-155 in PBMC was also negatively correlated with TNFα, IL-6, and NF-kB activity, which was associated with diabetes complications)." (PMID 33540559, 2021). "Diabetes has been shown to be an inflammatory process associated with elevated levels of interleukin-1, interleukin-6, C-reactive protein, and tumor necrosis factor-α throughout the body." (PMID 34772392, 2021). "TNF-α and IL-6 are important inflammatory factors involved in inflammatory response, often used as diagnostic indicators of diabetes and related complications such as diabetic nephropathy." (PMID 35004803, 2021). "The rs5186, rs1800629, rs1799983 and rs1800795 variants in the AGTR1, TNFA, NOS3 and IL6, respectively, are therefore relevant to diabetes and associated complications." (PMID 33820928, 2021). "Dysregulation of IL-6 and IL-10 are associated with increased risk of developing Type 2 Diabetes Mellitus (T2DM)." (PMID 33858419, 2021). "Il-6 has been shown to reduce insulin sensitivity in hepatocytes and has also been shown to be an independent predictor of type 2 diabetes mellitus and its associated cardiovascular events." (PMID 33868439, 2021). "There are studies, such as the ADVANCE trial, which indicate that patients with diabetes mellitus and elevated IL-6 would have a higher risk of developing heart failure." (PMID 33535417, 2021). "Conversely, lymphocytes, creatinine, albumin, troponin T, Pro-BNP, procalcitonin, ferritin, and IL-6 were found to have more impact in subjects with pre-existing diabetes than in those with COVID-associated hyperglycaemia." (PMID 34439986, 2021). "To further investigate the role of IL-6 in diabetes-associated renal fibrosis, we injected (IP) IL-6 neutralizing antibody in nondiabetic and diabetic CD-1 mice." (PMID 33888696, 2021). "The expression of PC1/3 and the production of GLP-1 and glucagon are increased in response to the diabetes-related pro-inflammatory cytokine, IL-6, in isolated human and mouse islets, and in the db/db, and ob/ob mouse models of obesity-associated diabetes." (PMID 34659118, 2021). "Older age, hyperphosphatemia, dialysis duration, diabetes mellitus, IL-6, and the NLR are associated with CAC." (PMID 34315328, 2021). "Age, diabetes, IL-6 and MMP-9 were significantly associated with a stiffness of ≥7.2 kPa in the multivariate model that included both demographic factors and serum-based markers (ghrelin, IL-6, TNFα and MMP-9)." (PMID 34813621, 2021). "Our results shows that odds of heart attack increase by 20 fold if diabetes is associated with high levels of triglycerides, TNFα and IL6 in addition with low levels of HDL-C." (PMID 33510184, 2021). "The gene coding interleukin 6 (IL‐6) is a promising candidate in predisposition to type 2 diabetes mellitus (T2DM)." (PMID 33960655, 2021). "The IL-6 regulatory genes were closely associated with vascular diseases, cardiovascular diseases, respiratory diseases, and diabetes mellitus." (PMID 33520118, 2021).
diabetes (continued). "It has been known that both diabetes and obesity cause a low grade pro-inflammatory state in the body with increased secretion of cytokines including interleukin (IL)-1, IL-6, IL-8 and tumor necrosis factor-α (TNF-α)." (PMID 34690930, 2021). "IL6 is an important inflammatory factor, and its function involves a variety of inflammation-related disease states, including diabetes mellitus susceptibility and systemic juvenile rheumatoid arthritis." (PMID 33880122, 2021). "In our study, it was demonstrated that CAC was common in CKD patients; moreover, older age, hyperphosphatemia, dialysis duration, diabetes mellitus, IL-6, and NLR were associated with the prevalence of CAC." (PMID 34315328, 2021). "A higher intake of total and insoluble dietary fiber has been found to reduce the risk of diabetes by lowering the levels of inflammatory markers (such as fibrinogen activator inhibitor-1, resistin, C-reactive protein, and interleukin-6)." (PMID 34276373, 2021). "Scientific evidence also suggests the inflammatory factors, tumor necrosis factor-α (TNF-α) and interleukin-6 (IL-6), are well known to be associated with the development of renal disease in diabetes." (PMID 32076626, 2020). "Inflammatory cytokines, including TNF-α and IL-6 are associated with diabetes and are linked to increased macro-vascular disorders." (PMID 33680027, 2020). "Inflammatory markers are significantly associated with diabetes, and elevated levels of IL-6 can increase the risk of diabetes by 31%, indicating that air pollution can affect the development of diabetes through systemic inflammatory responses." (PMID 33134393, 2020). "Hyperglycemia (a hallmark of diabetes) has been demonstrated to decrease the basal levels of SOCS3 (an endogenous negative regulator of IL-6-induced STAT signaling), while increasing nuclear phosphorylated-STAT3 in keratinocytes." (PMID 32365896, 2020). "Diabetes itself is linked to higher circulating IL-6 levels, and in turn, diet has been linked to IL-6 as well." (PMID 33134238, 2020). "On the other hand, the diabetes-induced expression of proinflammatory cytokines such as Tnf-α, Il-1β, and Il-6 was substantially diminished by Pdk2-deficiency." (PMID 33219201, 2020). "Diabetes is associated with an increase in inflammatory cytokines, such as tumor necrosis factor and interleukin 6 have detrimental effects on muscle mass, strength, and physical performance in older adults." (PMID 33076841, 2020). "In this scenario, positive associations were observed between IL-6 and PCR that remained after adjusting for body mass index, family history of diabetes, smoking, exercise, alcohol use, and hormone replacement therapy." (PMID 31799981, 2020). "Existing clinical data indicate that diabetes, as a whole, is strongly associated with elevated levels of IL-6, TNF-α, CRP, and adiponectin in Mexican Americans." (PMID 30868076, 2019). "The inflammatory process in diabetes is associated with the secretion of inflammatory cytokines by endothelial cells, e.g., tumor necrosis factor alpha (TNFα) and interleukin 6 (IL-6), and with the reduction of cell proliferation." (PMID 30610442, 2019). "On genotype analysis, the major allele G of IL-6 -174G>C was reported to be a risk factor for type 2 diabetes mellitus in Indian population." (PMID 30635365, 2019). "IL-6-deficient mice display an early phase delay in wound healing similar to that observed herein with hyperglycemic mice, and IL-6 dysregulation is a well-known hallmark of diabetes." (PMID 31073533, 2019). "Another study found that the testosterone treatment led to the suppression of TNF, IL-1, and IL-6 released from cultured peripheral blood monocytes isolated from type 2 diabetes mellitus men with an androgen deficiency." (PMID 31500378, 2019). "In the covariate models, higher age was associated with increased TNF-α and IL-6, and presence of diabetes with higher concentrations of TNF-α, IL-6, and IL-10." (PMID 31755034, 2019).
diabetes (continued). "In a 2013 meta‐analysis, a dose‐response relationship between IL‐6 and risk of new onset T2D was observed, suggesting that inflammatory dysregulation exists prior to diabetes diagnosis." (PMID 30666661, 2019). "We also analyzed correlations with the systemic inflammatory biomarkers hsCRP and IL-6, which have previously been linked to incident diabetes in HIV positive individuals." (PMID 29795574, 2018). "This suggests that IL-6, as an inflammatory mediator, is responsible for some underlying changes that contribute to the development of diabetes." (PMID 30914847, 2018). "IL-6 and TNF-α, as major inflammatory factors, participate in the development of T2DM; the increasing expression of TNF-α and IL-6 can cause pathological injury and diabetes complications." (PMID 30544624, 2018). "In the MESA Study, including 5597 individuals (12% with diabetes), IL-6 was positively associated with NTproBNP throughout its whole range of values." (PMID 28946871, 2017). "The -174 G allele of the IL-6 gene has been associated with the development of the metabolic syndrome and diabetes as well as atherosclerosis in the context of chronic stress." (PMID 27555379, 2017). "This study aimed to investigate the association of plasma TNF-α, IL-6, and lL-10 levels and cytokine gene polymorphisms [TNF-α (-308 G→A), IL-6 (-174 C→G) and IL-10 (-1082 A→G, -819 T→C and -592 A→C)] in type 2 diabetes mellitus (T2DM) and obese patients." (PMID 28225860, 2017). "Other well-known diabetes-associated molecules such as fibrinogen, IL-1 β and IL-6 were among other very highly ranked predictors." (PMID 28846711, 2017). "While we observed poor performance of IL-6 in our Luminex bead assay as evidenced by a low level of detection, its soluble receptor, sIL-6R, was associated with a history of self-reported diabetes." (PMID 28753646, 2017). "Fetuin-A levels were associated with age, diabetes mellitus, and a previous kidney transplant, the Charlson comorbidity index, levels of IL-6, homocysteine, ADMA, or malondialdehyde and the daily dose of calcium salts." (PMID 28882110, 2017). "We found that the increased risk of breast cancer by diabetes was more obvious among women with the CC genotype than those with CG/GG genotypes of IL-6 rs1800796." (PMID 28591216, 2017). "The elevated levels of inflammatory markers, including C-reactive protein (CRP), tumor necrosis factor alpha (TNF-α), and interleukin 6 (IL6) are supposed to be associated with type 2 diabetes mellitus (T2DM)." (PMID 28716139, 2017). "In contrast, low-level chronically elevated circulating IL-6 (2–3 pg/mL) has been reported to be associated with an increased risk of developing diabetes and is reviewed elsewhere." (PMID 28512447, 2017). "We did not observe any significant association between the candidate IL6 SNPs and diabetes, across three genetic models." (PMID 26911440, 2016). "Diabetes is associated with constitutive low grade inflammation characterized by elevation of pro-inflammatory cytokines such as IL-6 and IL-6 is a potent inducer of NETs13." (PMID 27811985, 2016). "The partial duodenal switch was efficient to control one year after the procedure the chronic inflammatory process caused by the diabetes mellitus type 2 with BMI <35 by dropping the IL6 levels and bringing the HbA1c to normal." (PMID 28076480, 2016). "Lastly, the robustness of hubs was determined by challenging islets with cytokine cocktails (IL-1β/IL-6 or IL-1β/TNF-α) to re-create the pro-inflammatory milieu thought to be associated with diabetes." (PMID 27452146, 2016). "IL-6 is a pleotropic cytokine that regulates both pro- and anti-inflammatory cytokine production, and it has both protective and pathogenic roles in diabetes." (PMID 27783671, 2016). "Neutrophils are rich source of IL-6 and both elevated homocysteine and IL-6 levels have been demonstrated in diabetes associated pathologies." (PMID 27811985, 2016).
diabetes (continued). "Hypomethylation of IL6 was associated with raised levels of serum IL-6 in patients with rheumatoid arthritis, and with body weight among diabetes patients." (PMID 26911440, 2016). "We derived interaction terms between PM10 and genotypes, and applied mixed logistic models to explore genetic interactions by IL6 polymorphisms on the odds of diabetes." (PMID 26911440, 2016). "We found a modifying effect of IL6 -572G > C polymorphism on the association between air pollutants and diabetes, where carriers of the pro-inflammatory GG genotype were most susceptible." (PMID 26911440, 2016). "Vascular calcification is associated with age, dialysis duration, hypertension, diabetes mellitus, calcium and phosphate ions, parathyroid hormone, vitamin D, and inflammatory cytokines such as interleukin-6 (IL-6) in HD patients." (PMID 26914918, 2016). "Inflammatory cytokines such as TNF-α, IL-6, and IL-1β can cause adipocyte dysfunction, which is involved in the development of diabetes." (PMID 27878229, 2016). "The association between AF and IL-6 remained significant after adjusting for age, sex, race, BMI, smoking, diabetes mellitus, history of CVD, laboratory variables, SBP, echo parameters, medication use and kidney function." (PMID 26840403, 2016). "The cited works have shown that the reduced level of IL-6 is associated with the impaired wound healing in diabetes." (PMID 26861982, 2016). "NF-κB regulates the expression of enzymes (such as COX-2 and iNOS), cytokines (such as TNF, IL-1, IL-6, IL-8), adhesion molecules and has been linked with age-related diseases such as atherosclerosis, diabetes, osteoporosis, Alzheimer’s disease, and cancer." (PMID 25871293, 2015). "After 10 weeks of feeding, the elevated plasma glucose, TNF-α, and IL-6 and lower adiponectin levels caused by diabetes were effectively reversed by chitosan treatment." (PMID 25871293, 2015). "Age, increased BMI, diabetes, low ejection fraction, left main stenosis, and genetic variation in the IL-6 promoter were established as significant independent risk factors for the survival of patients with three-vessel disease." (PMID 25526459, 2014). "IL-6 levels significantly correlated with infection (P = 0.02), and IP-10 levels were directly associated with diabetes mellitus (0.02), male sex (0.01), and Hispanic ethnicity (0.04)." (PMID 22121485, 2012). "Although the association between IL-6, CVD, and CVD risk factors such as diabetes has been recognized in previous cohorts, few studies have examined the association between serum IL-6 and CVD mortality." (PMID 22514624, 2012). "We also estimated associations among those with both CHD and diabetes (n = 76), finding that for IL-6 and IL-8, associations with BC were stronger than those for either condition alone." (PMID 22336131, 2012). "Accordingly, elevated levels of IL-6 also predicted an increased risk of diabetes in postmenopausal women and in the current study." (PMID 22615828, 2012). "Even after adjusted for compounding factors like TNF-α, IL-6, and leptin, adiponectin stood as independent marker of association with genetic predisposition for future development of diabetes (P < 0.01)." (PMID 23213322, 2012). "In the EPIC-Norfolk cohort, higher ferritin level was associated with diabetes risk after adjustment for conventional risk factors as well as plasma levels of vitamin C, C-reactive protein, fibrinogen, IL-6, liver function tests, ALT, GGT and adiponectin." (PMID 22752055, 2012). "Further, we also found that the presence of both CHD and diabetes conferred the greatest sensitivity to BC-associated changes in IL-6 and IL-8." (PMID 22336131, 2012). "Here, we extend these findings by showing that individuals with diabetes carrying the null allele for GSTM1 also have the most pronounced changes in IL-6, RBC, total hemoglobin and MCV." (PMID 20525188, 2010).
diabetes (continued). "The available biological data have strongly suggested that T2D is an inflammatory disease.Various markers of inflammation predict the future diabetes risk, including IL-6, CRP, sialic acid, and orosomucoid." (PMID 20976133, 2010). "Increased serum levels of IL-6 have been found in patients with stroke or type 2 diabetes mellitus and IL-6 is suggested to increase the risk of coronary artery disease." (PMID 16566827, 2006). "Targeting PTH1R upregulation and the IL-6 signaling pathway in osteocytes could represent a novel therapeutic approach to mitigating bone complications associated with diabetes." (PMID 41751813, 2026). "Patients with elevated levels of IL-6 and IL-1β have a higher risk of even developing diabetes." (PMID 41000474, 2025). "Univariate analysis showed that diabetes, preoperative serum CK levels, serum IL-6, and TNF-α levels at postoperative day 3 were associated with early LFCN injury, while diabetes, BMI, and postoperative inflammation were significantly associated with persistent LFCN injury." (PMID 40236989, 2025). "Furthermore, this study examined IL6, an inflammatory cytokine implicated in the pathogenesis of diabetes as well as stimulating an inflammatory response." (PMID 40657379, 2025). "Some studies have demonstrated that increased levels of pro-inflammatory cytokine caused by diabetes (e.g., IL-6, TNF-α) inhibit muscle protein synthesis, promote protein degradation, and impair muscle function, which are inversely associated with muscle strength." (PMID 40354753, 2025). "Finally, the T2DM-specific dissociation in the results of the association between IL-6 and diabetes-specific biomarkers (plasma Glucose and HbA1c)." (PMID 40606939, 2025). "Notably, the impact of the IL-6 pathway on diabetes risk in the general population appears to be small." (PMID 41302503, 2025). "Increased IL-6 levels have been linked to more severe periodontal destruction, especially in individuals with poor glycemic control, indicating a synergistic effect between diabetes and periodontal disease." (PMID 40283677, 2025). "First, biomarkers such as adiponectin, CRP, and IL-6 could be integrated into screening protocols to better identify individuals at risk of lean diabetes." (PMID 41523554, 2025). "We then examined whether the expression of HMGA2, PPARG, ADIPOQ and IL6 was associated with diabetes remission." (PMID 40740163, 2025). "In “case-mix + laboratory”-adjusted logistic regression analyses, we observed that female sex, diabetes, presence of an arteriovenous fistula/graft, and lower serum albumin, IL-6, and adiponectin levels were significantly associated with the highest tertile of leptin." (PMID 41295840, 2025). "Notably, IL-6 has been linked to diabetes and cardiovascular events, while CXCL8 has been associated with an unfavorable metabolic and lipid profile in type 2 diabetes." (PMID 41030257, 2025). "The IL-6 rs1800795 polymorphism may have different effects in different pathologies such as diabetes mellitus and may also vary depending on the ethnic origins of patients, such as Asians and mixed populations." (PMID 39458264, 2024). "Other research found that IL6 and IL8 appeared to play important roles in the development of diabetes and related complications, and this is consistent with our correlation analysis, which showed that the level of IL6 was associated with a lower eGFR and a longer duration of diabetes." (PMID 39525855, 2024). "Considering the critical role of NF-κB in orchestrating the inflammatory response through the upregulation of pro-inflammatory genes, we sought to elucidate the intricate interplay between TNF-α, IL-6, and NF-κB in the context of diabetes-associated inflammation." (PMID 39496097, 2024). "The condition is linked to higher levels of IL-18, TNF-α, and IL-6, indicating inflammation that may drive type 2 Diabetes Mellitus (T2DM)." (PMID 40027364, 2024).